CD4 (CD4 molecule)
Diseases named in the same sentence as CD4 in open-access papers (continued):
Sharing a sentence is not in itself a finding about the gene and the disease.
psoriasis (continued). "We found that topical ozone treatment significantly decreased patients' psoriasis area and severity index (PASI) scores and the expression of psoriasis-associated cytokines in their peripheral blood CD4+ T cells." (PMID 32398953, 2020). "Although inflammation mediated by CD4+ Th17 T cells is considered an important trigger in the development of psoriasis, the precise underlying immuno-inflammatory mechanisms are still to be fully defined." (PMID 31214201, 2019). "In the present study, we integrated psoriasis GWAS association variants with publicly available functional genomic data in CD4+ primary T cells, and achieved a relatively comprehensive catalog of PFVs in psoriasis GWAS regions." (PMID 29715312, 2018). "In psoriasis, T-cells (both CD4+ and CD8+) are known to cause low production of Th2 cytokines (IFNγ, TNFα, and IL-2) and high production of Th1 cytokines (IL-4, IL-6 and IL-10), leading to polarization of the type 1 pathway." (PMID 26849645, 2016). "Several of the top-ranked genes according to significance of the correlation in CD4+ cells are known to be associated with psoriasis." (PMID 22291603, 2012). "Psoriatic epidermis is known to contain a significantly higher CD8 to CD4 T cell ratio than the dermis and also a strong association of psoriasis with HLA-Cw6 has been reported, a MHC class I molecule involved in antigen presentation to CD8 T cells." (PMID 21124836, 2010). "Furthermore, PIEZO1 facilitated keratinocyte-mediated CD4 + T cell differentiation into Th17 cells, a key pathogenic factor in psoriasis." (PMID 40495117, 2025). "The pleiotropic impact of IL-16 on immune system cells and its association with CD4+ lymphocytes suggest that this cytokine may be involved in the pathogenesis of psoriasis." (PMID 40731810, 2025). "Such evidence not only strengthens the biological plausibility of our Mendelian randomization results but also indicates that these genes may serve as critical immunoregulatory mediators in CD4+ T cell–driven inflammatory responses associated with psoriasis." (PMID 41328434, 2025). "K14/Gpx4 mice also developed signs of psoriasis-associated systemic inflammation — elevated serum proinflammatory cytokines (e.g., IL-6), an increase of splenic CD4+ and CD8+ T cells, CD4+ T cell infiltration of the hind-paw synovium, neutrophilic infiltration of the liver and the lungs." (PMID 39570671, 2024). "Moreover, cutaneous Staphylococcus aureus which is enriched in psoriatic and Streptococcal pyogenes that is associated with the onset of some types of psoriasis was identified to trigger a TH17 polarization of CD4+ T cells." (PMID 38642273, 2024). "Patients with CD4 counts <200 cells/mm3 are at increased risk for severe psoriasis." (PMID 38238209, 2024). "The aim of this study was to investigate disease-associated DNA methylation patterns in CD4+ T-cells from psoriasis and PsA patients that may represent potential diagnostic and/or prognostic biomarkers." (PMID 37662940, 2023). "The aim of this study was to identify disease-associated DNA methylation signatures in CD4+ T-cells from patients with psoriasis and PsA that may be used as diagnostic and/or prognostic biomarkers to inform treatment and care." (PMID 37662940, 2023). "STAT3 plays a critical role in differentiating both Th17 cells and Tregs from naïve CD4+ precursors, and the mechanism by which miR-125a-5p regulates the immune response of CD4+ T cells in psoriasis pathogenesis may also be associated with STAT3." (PMID 37773129, 2023). "In fact, CD4+ T cells, particularly Th1 and Th17 cells to produce pro-inflammatory cytokines, cause chronic inflammatory skin diseases (e.g., atopic dermatitis and psoriasis) by leading to a sustained and amplified inflammatory status." (PMID 33808279, 2021). "In Goh's study, CD4 counts <200 were remarkably associated with psoriasis and drug reactions." (PMID 32850174, 2020).
psoriasis (continued). "In order to investigate the potential mechanisms of ozone action on psoriasis, we assessed the expression levels of common psoriatic-associated cytokines and transcription factors in CD4+ T cells from the patients' peripheral blood using quantitative real-time PCR (qPCR)." (PMID 32398953, 2020). "In particular, miR-200c was shown to decrease in peripheral blood mononuclear cells of psoriasis patients compared to control, and miR-200a was shown to be upregulated in CD4+ T cells, causing immune dysfunction through Th17/Treg cells and relevant cytokines in psoriasis vulgaris patients." (PMID 31929856, 2019). "The result is compatible with previous reports, as AhR-deficiency in mice resulted in reduced IL-22-secreting CD4+ T cells and more specifically, a psoriasis model demonstrated the requirement of AhR for IL-22 production by Th17, but not by ILC3 and γδ+ T cells." (PMID 30944419, 2019). "In this study, the elevated expression of Notch1 and its target gene Hes-1 was demonstrated in peripheral CD4+ T cells of PV patients and positively associated with psoriasis area and severity index, which indicates that Notch1 signaling participates in the development and progress of PV." (PMID 29686529, 2018). "Additionally, psoriasin is a chemotactic for CD4+ T cells and neutrophils, and is induced by psoriasis-associated inflammatory cytokines that include IL-1β, IL-17, IL-22, and TNF-α." (PMID 28360856, 2017). "In both human psoriasis and murine models of psoriasiform inflammation, IL-23 is predominantly produced by myeloid DCs and promotes the expansion of pathogenic IL-17A-producing γδ T cells and CD4+ Th17 cells." (PMID 28469254, 2017). "Finally, there is an emerging a role for CD4 T cells recirculating between skin and blood in the clinical manifestations of psoriasis and the associated comorbidities." (PMID 27595115, 2016). "The pleiotropic impact of IL-16 on immune system cells and its association with CD4+T cells suggest that this cytokine might be involved in the pathogenesis of psoriasis." (PMID 27788245, 2016). "The opposing effects of class II HLA alleles in AD and psoriasis might represent the differential responses to pathogenic and allergenic peptides presented to CD4+ T cells." (PMID 25574825, 2015). "They found that in CD4+ cells, in a combined analysis of DNA methylation and gene expression, a significant deference of methylation of specific genes known to be involved in immune response and associated with psoriasis." (PMID 25208211, 2014). "Recently, T cell-targeted monoclonal antibodies such as the anti-IL-17A agent secukinumab, anti-CD4 monoclonal antibody, and cytotoxic T lymphocyte-associated antigen 4-immunoglobulin have demonstrated significant therapeutic efficacy in the treatment of psoriasis." (PMID 32817748, 2020). "This study aimed to elucidate the expression patterns of EZH2 in peripheral blood mononuclear cells (PBMCs) from psoriasis patients, with a focus on CD4+ T cells, CD8+ T cells and monocytes." (PMID 41518566, 2026). "Current in vitro models recapitulate psoriasis-like pathology by incorporating CD4+ T cell subsets into skin equivalents, but lack CD8+ T cells, key mediators of epidermal inflammation and chronic disease." (PMID 42039187, 2026). "The results reveal that repeated induction of psoriasis-like inflammation results in a significant expansion of memory T cells, with a reduction in naïve CD4+ and CD8+ T cell populations." (PMID 40599782, 2025). "Patients with psoriasis suffer from immune system dysregulation, characterized by various differentiated subpopulations of CD4+ T cells." (PMID 40520230, 2025). "The depletion of CD4+ T cells in HIV patients disrupts the immunological balance, perhaps favoring pro-inflammatory pathways mediated by Th17 cells, which are linked to psoriasis pathogenesis." (PMID 40724556, 2025). "CXCR3 expression was strongly upregulated on TCM, TEM and terminal effector CD4+ T cells in the recurrent psoriasis-like group." (PMID 40599782, 2025).
psoriasis (continued). "In psoriasis, Th1 and Th17 cells, as pivotal CD4+ T cell subsets, play central roles in disease pathogenesis." (PMID 40948748, 2025). "These advances highlight the importance of IL-17 and emphasize the critical importance of studying CD4+ T cell differentiation and secretion of inflammatory factors in elucidating the pathogenesis of psoriasis." (PMID 40520230, 2025). "A marked decrease in the percentage of naïve T cells was observed in recurrent psoriasis-like inflammation as compared to the control condition in both the CD4+ and CD8+ compartments." (PMID 40599782, 2025). "CD immune markers: Psoriasis features an exaggerated immune response, with the infiltration of CD4+ and CD8+ T cells, dendritic cells such as CD11c+, and other leukocytes." (PMID 40731810, 2025). "Specifically, in psoriasis, the early infiltration of activated CD4+ T cells into the epidermis acts as a key trigger for inflammation and keratinocytes hyperproliferation." (PMID 40406126, 2025). "CD4 + CD25 + T cells generated in vitro from the hematopoietic cells of psoriasis patients exhibit diminished regulatory functions." (PMID 40690118, 2025). "The development of psoriasis involves numerous inflammation-related genes, including TNF (encoding tumor necrosis factor), CD4 (encoding the CD4 molecule), IL-10 (encoding Interleukin-10), and IL-4 (encoding Interleukin-4)." (PMID 40678620, 2025). "In psoriasis samples, there was an increase in T cells CD4 memory activated, T cells follicular helper, and Macrophages M1, while a decrease was observed in B cells memory, plasma cells, and mast cells resting." (PMID 40093802, 2025). "One of the most recent and promising developments in psoriasis research is the definition of the role of the Th17 CD4+ T cell and one of its cytokines, IL-17, in the disease’s pathophysiology, progression, and maintenance." (PMID 40243580, 2025). "Particularly, psoriasis‐specific self‐antigens presented by dendritic cells (DCs) initiate the activation and clonal expansion of antigen‐specific CD4+ T cells, which subsequently secrete excessive cytokines." (PMID 39665264, 2025). "Although their sample was small (n = 48), these findings are important, as CD4+ cells and monocytes participate in skin infiltration preceding plaque formation in psoriasis." (PMID 39959848, 2025). "Concurrently, migrating neutrophils overexpress matrix metalloproteinase-9 (MMP-9), promoting psoriasis progression by inducing vascular remodeling, enhancing endothelial activation, and driving the accumulation of CD4+ T cells." (PMID 41009795, 2025). "While the pathophysiology of psoriasis remains incompletely understood, the critical involvement of CD4+ T cells is established." (PMID 41328434, 2025). "Interleukin-21 has been shown to contribute to psoriasis pathogenesis via the proliferation of CD4+ T cells, increasing function and differentiation of Th17 cells, and downregulation of regulatory T cell (Treg) cell differentiation." (PMID 40161116, 2025). "One of the most recent and promising developments in psoriasis research is the definition of the role of the Th17 CD4+ T cell and one of its cytokines, interleukin 17 (IL-17), in the disease pathophysiology, progression, and maintenance." (PMID 40243580, 2025). "Altogether, these results highlight qualitative differences among LL37-, cit-LL37-, and carb-LL37-specific CD4 T cells, in patients with psoriasis." (PMID 40270954, 2025). "In mouse models of psoriasis, a one-time BoNT-A injection significantly decreased cutaneous infiltration of CD4+ lymphocytes." (PMID 40278661, 2025). "There is a strong connection between immune cells and psoriasis, specifically CD4 + T cells which create IL-9 and γά T cells which produce IL-17." (PMID 40690118, 2025). "CD4+ T cells were pivotal in both diseases, promoting keratinocytes proliferation in psoriasis and exacerbating intestinal inflammation in CD through cytokine secretion." (PMID 40406126, 2025).
psoriasis (continued). "Significantly more CD4(+)/CD8(+) double-positive cells were observed in AD than in psoriasis (mean: 1.4% [standard deviation: 0.7%] vs. 0.5% [standard deviation 0.3%], respectively; P < 0.05)." (PMID 39938773, 2025). "In vitro experiment, on the other hand, demonstrated that co-cultures MSCs inhibited CD4+T-cell activation and differentiation, an important aspect of psoriasis pathogenesis." (PMID 40748586, 2025). "The infiltration of IL-17A–positive CD4+ T cells, γδ T cells, and neutrophils was observed in the skin at the experimental endpoint and in human psoriasis, suggesting a critical role of the damaged skin–derived immune cells in systemic IL-17A production." (PMID 39919800, 2025). "Hhsa-miR-106a-5p, which is part of the in vitro CD4 T cell-derived miRNA signature, is upregulated in serum from psoriasis patients and it is specific in Th1/Th17 cell-derived extracellular vesicles (EVs) in vitro." (PMID 40725409, 2025). "Based on this scoring system, CD4+ T cells were found to have the most prominent contribution to psoriasis." (PMID 41328434, 2025). "The skin model with normal keratinocytes showed a strong expression of the psoriasis marker S100A7 if activated CD4+ T cells were integrated." (PMID 40678130, 2025). "In psoriasis, skin inflammation is dominated by CD4+ and CD8+ T-cells, with CD8+ T-cells emerging as key players." (PMID 39859462, 2025). "Conversely, patients with guttate psoriasis have a higher proportion of IL-17+ CD4+ cells compared to those with plaque psoriasis." (PMID 40303401, 2025). "In psoriasis, the major circulating immune cell lineages operational in the disease pathophysiology include neutrophils, low-density granulocytes, monocytes, and CD4+ T cells." (PMID 40815832, 2025). "The expression of T-cell immunoreceptor with immunoglobulin andimmunoreceptor tyrosine-based inhibitory motif domains (TIGIT) on circulating CD4 T cells correlates with psoriasis severity." (PMID 40391222, 2025). "In psoriasis, increased infiltration by CD4+ T lymphocytes is already elaborated in many studies apart from CD8+ T lymphocytes by CXCL16-CXCR6 associations." (PMID 40724556, 2025). "Proinflammatory cytokines produced mainly by effector cluster of differentiation 4-positive (CD4+) T helper 17 (Th17) cells contribute to the pathogenesis of psoriasis." (PMID 40948686, 2025). "To address further differences among the native LL37- and modified LL37-specific CD4 T cells, we analyzed T-helper follicular (Thf) cells, which can be altered in psoriasis according to a prior study." (PMID 40270954, 2025). "This provides us with a new approach to achieve plasticity in CD4+ T cell differentiation by regulating the content of lncRNA, thereby improving the progression of psoriasis." (PMID 40520230, 2025). "Psoriatic skin lesions contain high numbers of CD4 + T cells that produce IL-17, indicating that Th17 cells play a crucial role in the immunopathogenesis of psoriasis." (PMID 40690118, 2025). "Our findings support these observations and demonstrate an increased proportion of monocytes, M1 macrophages, M2 macrophages, activated dendritic cells, and CD4 memory resting T cells in the lesional skin of psoriasis patients." (PMID 39014096, 2024). "We compared the effects of fire acupuncture plus TCM versus TCM alone on the CD4+/CD8+ lymphocyte ratio in the peripheral blood of patients with psoriasis." (PMID 38363920, 2024). "TIGIT plays a role in inhibiting CD4 + T cell responses and has been reported to be downregulated in psoriasis." (PMID 39684538, 2024). "Two research teams reported elevated and decreased genome-wide methylation levels in CD4+ T cells from psoriasis patients, respectively." (PMID 39296901, 2024). "Methotrexate, a cornerstone medication in psoriasis treatment, has been proven to modulate linoleic acid metabolism within CD4+ central memory T cells and CD8+ effector memory T cells." (PMID 38529280, 2024).
psoriasis (continued). "In our research, based on analyses of three independent datasets, we have discovered that the primary immune cell types present in the skin tissues of psoriasis patients were resting mast cells, M2 macrophages, and resting CD4 memory T cells." (PMID 39239353, 2024). "In the context of HIV infection, psoriasis patients present with atypical clinical manifestations, more severe disease, and more recalcitrant treatment as CD4 + T cell counts decrease." (PMID 39605044, 2024). "In a previous study, we examined the SEB impact on the phenotype and function of CD4 lymphocytes from psoriasis patients." (PMID 39582772, 2024). "This study aimed to assess the interplay between the epidermal barrier tight junctions, the microbiota, and the immune response mediated by CD4 T cells, in psoriasis pathogenesis." (PMID 39582772, 2024). "Classification of the GSE151177 psoriasis dataset yielded nine clusters, which we annotated into five cell populations based on common immune cell marker genes: CD4+T cells, CD8+T cells, natural killer cells (NK), macrophages, and DCs." (PMID 38917217, 2024). "on skin tissue from a patient with psoriasis and vitiligo comorbidity revealed elevated levels of CD4, CD8, Foxp3, and IL‐17A in the comorbid skin tissue." (PMID 39031921, 2024). "In seven CD4+ T cell clones expanded from the affected skin of an untreated patient with psoriasis, IL-8 was expressed by skin-derived T cells." (PMID 39409000, 2024). "In this investigation, we found that CD28 on CD39+-activated Treg and CD25 on CD39+ CD4 Treg were protective against psoriasis." (PMID 38558803, 2024). "IL-33 can worsen the condition of IMQ psoriasis model mice, reduce CD4 + T and CD8 + T cells in the spleen of psoriatic mice, inhibit autophagy in the skin, and promote STAT3 tyrosine phosphorylation." (PMID 38255845, 2024). "In murine models of psoriasis, injection of botulinum toxins (both A and B) reduces accumulation of CD4 and CD11 cells and IL17 within the psoriatic lesion, as well as decreasing the level of cytokines." (PMID 39453225, 2024). "HIV infection can trigger and worsen psoriasis, and this probability increases in patients with greater immunosuppression, who have a low count of CD4 + T lymphocytes." (PMID 38238209, 2024). "Previous studies have shown that the proportion of CD4+ CD28null T cells is inversely correlated with the severity of psoriasis." (PMID 38590608, 2024). "In the psoriasis group, monocytes and M1 macrophages were positively correlated with CD4+T cells and NK cells." (PMID 38917217, 2024). "The number of dendritic cells, marked by CD86 and CD80 antibodies and playing a critical role in the local inflammatory response in psoriasis, and CD4+ cells in the dermis was also decreased after TBTDC NP-PDT." (PMID 39109246, 2024). "The effects of CD4+ helper T cells in psoriasis can be observed in grafted skin with injected cells from psoriasis patients into graft sites on severe combined immunodeficiency disease (SCID) mice." (PMID 37942312, 2023). "CitLL37 also induced a significant increase in the proportion of IL-10-producing CD4+ T cells from patients with psoriasis compared to unstimulated cultures and cultures stimulated with native LL37, and a similar tendency was observed in the HD group." (PMID 38173716, 2023). "It has been well established that CD4 + Foxp3 Treg cells play an indispensable role in suppressing autoimmune inflammatory responses, including psoriasis." (PMID 37506136, 2023). "To test a functional consequence of the miR‐31‐induced secretome, we tested differentiation of naïve CD4+ T cells towards Th17 cells, as this T cell subtype specifically marks psoriasis." (PMID 36855912, 2023). "DNA methylation profiles in CD4+ T-cells discriminate psoriasis patients from healthy individuals and skin psoriasis from PsA patients." (PMID 37662940, 2023).